SNORD115-2 (small nucleolar RNA, C/D box 115-2)
Synonyms: HBII-52-2
Gene: Small nucleolar RNA gene on chromosome 15 (25,172,635 to 25,172,716, forward strand). Ensembl gene ENSG00000199712.
Gene Ontology:
Biological process: RNA processing
Cellular component: nucleolus
Homologues: Orthologues: chimpanzee SNORD115 (99% identical). Paralogues in human: SNORD115-20 (94% identical), SNORD115-40 (94% identical), SNORD115-12 (93% identical), SNORD115-13 (93% identical), SNORD115-14 (93% identical), SNORD115-21 (93% identical), SNORD115-9 (93% identical), SNORD115-10 (91% identical), SNORD115-11 (91% identical), SNORD115-16 (91% identical), SNORD115-17 (91% identical), SNORD115-18 (91% identical), and 37 more.